IL6 (interleukin 6)
Diseases named in the same sentence as IL6 in open-access papers (continued):
Sharing a sentence is not in itself a finding about the gene and the disease.
infection (continued). "Using a multiplex assay, we analyzed the protein levels of interleukin (IL)-6, IL-8, monocyte chemotactic protein (MCP)-1 and matrix metalloprotein (MMP)-3 in the supernatant of infected IMR-90 cells at several times post-infection." (PMID 24116215, 2013). "The infection of J774A.1 macrophages resulted in an increase in TNF-α, IL-1β, and IL-6 expression; IL-10 was downregulated during Leishmania infection, although its expression recovered compared to noninfected macrophages." (PMID 23555077, 2013). "Consistent with this, il12a, il12b, ifng, il6, il17a mRNA expression were considerably increased in the brains of P. berghei ANKA-infected Alox5-KO vs. WT mice at 5 days after infection." (PMID 23613965, 2013). "At 3 dpi, IL-4, IL-6 and TNF were upregulated similarly in response to both virus strains and remained upregulated throughout the course of infection." (PMID 23342177, 2013). "When monocytes were infected with Mtb, followed by immediate treatment with PZA at 10 or 50 μg/ml, dose-dependent reductions in the levels of pro-inflammatory molecules TNF-α, IL-6, IL-1β and MCP-1, relative to infection alone, were observed." (PMID 24015316, 2013). "VACV infection induced the production of Cxcl10 and Il-6 into the bronchoalveolar lavage (BAL) fluid, however, infection with VACV vΔC16 lead to an enhanced production of these cytokines." (PMID 24098118, 2013). "Infection of HepG2 cells and PHH by HCMV resulted in the production of IL-6 and the subsequent activation of the IL-6R-JAK-STAT3 pathway." (PMID 23555719, 2013). "In this study, analysis from C. trachomatis infected macrophages revealed increased levels of GM-CSF, IL-1α, IL-1β, IL-6, TNF, IL-12p70, and IL-10 after a 2-day infection, with TNF, IL-6, and IL-1α being more robustly produced." (PMID 23766556, 2013). "The mRNA expression of IFN-γ, IL-1β, IL-6 and TNF in the frontal cortex and hippocampus of control and infected mice on day 5 post-infection were estimated by quantitative real time PCR." (PMID 24180288, 2013). "Some studies have demonstrated that upon infection, H. pylori activates the expression of a number of genes such as CagA, AKT, TNF-α, ATF3, IRX5, IL-6 and IL-8." (PMID 24069310, 2013). "The peripheral immune system normally produces various pro-inflammatory cytokines, including interleukin-1β (IL-1β), IL-6 and tumor necrosis factor-α (TNF-α) during infection." (PMID 24137231, 2013). "Upon in vitro infection with Lm, CYLD reduced NF-κB-dependent production of reactive oxygen species, interleukin (IL)-6 secretion, and control of bacteria in macrophages." (PMID 23825949, 2013). "Both live and UV inactivated virus elicited robust induction of inflammatory cytokines/chemokines such as IL-6, IL-8, TNF-α, and RANTES within 12 h of infection." (PMID 23671700, 2013). "The IL-6, mTOR, CXCR4 and PI3K signaling pathways were the most significantly affected at 12 weeks post-infection." (PMID 23448601, 2013). "Proinflammatory mediators such as IL-6, TNF-α, and MCP-1 increased over time during the course of infection." (PMID 23816343, 2013). "Activated NF-κB, also in chondrocytes, is known to be involved in the regulation of several genes, including by infection, adhesion, cell-cycle, apoptosis, survival and inflammatory processes, by activating IL-1β, TNF-α, IL-6, Cox-2 and MMPs." (PMID 24283517, 2013). "The bacterial proinflammatory effect of P. mosselii ATCC BAA-99 and MFY161 was then assessed by measuring the secretion of IL-6 and IL-8 cytokines in Caco-2/TC7 after 24 h of infection." (PMID 23718251, 2013). "Compared to the other inbred mouse strains investigated, C3HeB/FeJ mice displayed elevated serum levels of IL-6, TNF-α and extremely high levels of the chemokine CCL2 at 3 and 5 days post infection." (PMID 23617550, 2013).
infection (continued). "Unlike early TNFα synthesis that requires IFN-I after both i.p. and i.g. infection, the production of IL6 and MCP1 during the initial 24 h of infection is reduced specifically when bacteria enter their host via the intestine." (PMID 23840314, 2013). "During complicated infection, overly expressed TNF-α and IL-10 thus act to downregulates IL-6 production." (PMID 24324686, 2013). "We observed increased IL-6 production in the supernatants of HepG2 cells and PHH starting as early as 2 h post-infection, with both the HCMV-AD169 and HCMV-DB strains triggering the release of IL-6." (PMID 23555719, 2013). "In this study, a burst of IFN-γ, IL-6, and TNF-α was observed in lethal influenza virus-infected mice, especially on day 4 after infection." (PMID 24373231, 2013). "Protein levels of IL-6 were detected in DLN and footpads of M. ulcerans infected mice at day 33 post-infection." (PMID 23638204, 2013). "Previous investigators have observed significantly higher levels of pro- and anti-inflammatory cytokines (including IL-6, IL-8, MCP-1) in patients with severe A(H1N1)pdm09 infection." (PMID 23418448, 2013). "We found significantly elevated levels of IL-12p70 and IL-6 in IAV-infected MDDCs exposed to SP, while infection with either pathogen alone induced low or undetectable levels of both cytokines." (PMID 23421931, 2013). "Laboratory parameters in use for the rapid identification of infection include procalcitonin (PCT), interleukin 6 (IL-6), lipopolysaccharide binding protein (LBP), and CRP." (PMID 24349403, 2013). "The bacterial proinflammatory effect of P. mosselii ATCC BAA-99, P. mosselii MFY161 and P. aeruginosa PAO1 was assessed by measuring IL-6 and IL-8 secretion in Caco-2/TC7 after 24 h of infection." (PMID 23718251, 2013). "A variety of cytokines and chemokines were induced by both HRV 14 and/or HRV 16 infection that include FGF-Basic, chemokines and cytokines like IL-6, IL-15, MCP-2, IP-10, MIP-1β, type I IFN-α, type III IFN-λ2 (IL-28A), and ENA-78." (PMID 23799120, 2013). "Tanaka Y found the infection factors of gastrointestinal can activate PAR-2 receptor promoting inflammation medium release, such as IL-6, IL-8 and TNF- α." (PMID 24088410, 2013). "Considering the concentration of IL-6 and CXCL-2, there was an increase of these mediators after 24 h of infection, and this increase was maintained after 72 h of infection compared to control animals." (PMID 23991239, 2013). "Among the pro-inflammatory cytokines and chemokines tested, IL6 and MCP1 were decreased early after infection." (PMID 23840314, 2013). "Infection with influenza virus, a major ssRNA virus, induces a significant increase in the production of TNF-α and IL-6 by macrophages, leading to enhanced inflammatory responses." (PMID 24191131, 2013). "Apparently, the same cytokine profile, including IL-6, IL-8, IFN-γ, IL-10 and chemoattractants, exists in both porcine and human/NHP ZEBOV infection." (PMID 23626748, 2013). "The results of our study also demonstrate increased expression of pro-inflammation cytokines, IL-6, IL-1β and IFN-α, following LPAIV infection in vitro." (PMID 24252391, 2013). "We conclude that the IG count displays superior discriminative power for infection over CRP, LBP and IL-6, particularly within the decisive first 48 hours after the onset of SIRS." (PMID 23398965, 2013). "In contrast, resistant C57BL/6J mice displayed low serum levels of IFN-γ, TNF-α, IL-6, and CCL2 at both timepoints of infection." (PMID 23617550, 2013). "At 4 weeks post infection, IFNγ, IP-10, MIG, MCP-1, IL-17 and IL-6 were elevated in infected mice compared to the uninfected mice." (PMID 23469125, 2013). "Th17 cells exert their biological effects via the secretion of IL-17A, IL-17F, IL-6, IL-22 and TNF-α, which signals neutrophils to move towards the site of inflammation and play an infection-fighting role in the early stage of the immune response." (PMID 23403648, 2013).
infection (continued). "This study demonstrates that circulating hepcidin-25 concentrations are strongly predicted by both infection/inflammation markers (CRP and IL-6) and iron status markers (SF, ZPP and sTfR) in infants in rural sub-Saharan Africa." (PMID 23460869, 2013). "An infection with MAB induced the highest levels of cathelicidin LL-37 and hBD1 and intermediate levels of IL-6; however, little is known regarding the immunological response to MAB infection." (PMID 25436879, 2013). "Regarding the discriminative power for infection, the IG count was more indicative than other clinical parameters such as CRP, LBP and IL-6, which had a sensitivity of less than 68%." (PMID 23398965, 2013). "For example, IL-1β, IL-6, and TNF-α can be regarded as pro-inflammatory cytokines due to their role in early host defence against infection or disease, and in the development and progression of inflammation." (PMID 24146637, 2013). "Levels of IL-6 and CXCL-1 were higher in BAL of 5-LO−/− mice 72 h after infection compared with the same period in WT mice." (PMID 23991239, 2013). "Elevated production of cytokines, such as IL-6, TNF-α, and IFN-γ are very important for viral clearance in the early stage of infection by activating the innate immune system." (PMID 24159339, 2013). "A549 epithelial cells mainly produced the inflammatory cytokines IL-6 and TNF-α in an infection dependent process, while IL-8 was induced by live RSV and still in significant amounts by non-infectious virus." (PMID 24303065, 2013). "Of these, IP-10, IL-6, and TNF-α showed significantly attenuated responses to infection in FP-exposed mice." (PMID 22651370, 2012). "Second, CD11b+CD11c− APCs generated following CB4 infection produce lower levels of the inflammatory cytokines TNF-α and IL-6." (PMID 22355341, 2012). "Macrophages are known to synthesize and secrete cytokines, including TNF-α, IL1-β, IL-8, IL-6, IFN-γ and others, upon infection with Mtb." (PMID 23029190, 2012). "At 12 and 24 hours post infection RSV strains, NH1067 and NH1125 differed in their capacity to induce IL-6 by an order of magnitude or more." (PMID 22962966, 2012). "According to the study’s findings, simultaneous measurement of PCT, IL-6 and hs-CRP is more sensitive in diagnosis of neonate infections." (PMID 22708043, 2012). "Maximum IL-6 and TNF levels were observed at 2 days after infection and remained steady thereafter up to 4 days after infection, suggesting a complex interaction exists between C. trachomatis and macrophages." (PMID 22529524, 2012). "Additional cytokines representative of CAM were increased early post-infection in adult animals compared with mock-infected animals, including MCP-1, IL-6, and IL-12p40." (PMID 22792355, 2012). "After infection with each virus (104 PFU), lungs from three mice per group were collected at day 1, 3, 5 and 7 p.i. and the levels of cytokines (IL-6, IL-1β, TNF-α, IFN-γ) and chemokines (MIP-2, MIP-1α, MCP-1) in lungs were analyzed by ELISA." (PMID 22719870, 2012). "Inflammation is the first response of the immune system to infection or irritation; inflammation is mediated by cytokines such as TNF-α, IL-1β, IL-2, IL-6, and PGE2." (PMID 22919407, 2012). "Considering the remarkably similar production pattern of IL-6 and IL-8 in these SAH patients, it is perhaps particularly surprising that IL-8 production was quite resistant to modification by infection." (PMID 23176037, 2012). "Statistical analysis showed a significant difference in the ESDCs expression at all infection time points for MCP-1 and at 4 hours infection of IL-6 and TNFα compared to undifferentiated ESCs." (PMID 23284947, 2012). "The expression profiles of pro-inflammatory cytokines IL-6 and TNF-α in BALF after BJ501 infection were dramatically increased at 6 h." (PMID 22952892, 2012).
infection (continued). "Rather, RTD-1 administration appeared to protect infected animals by reducing pulmonary inflammation and suppressing IL-1α, IL-1β, IL-6, IL-12, CXCL1 (KC), CCL2 (MCP-1), CCL3 (MIP-1α), and CCL5 (RANTES) 2–4 days post-infection." (PMID 23236475, 2012). "MCMV replication promotes production of pro-inflammatory cytokines and chemokines (IL-12p70, IFN-γ, TNF-α, MIP-1α, IL-6, and MCP-1), which peak between 24 and 40 hours post-infection in the blood depending on the cellular source of the cytokine." (PMID 22649570, 2012). "AM from FP-treated mice showed impaired expression of infection induced TNF-alpha, IP-10 (CXCL-10), and interleukin 6 (IL-6), and AM also showed a trend towards impaired intracellular pathogen control following in vivo infection." (PMID 22651370, 2012). "When an infection occurs, peripheral monocytes/macrophages respond with the secretion of inflammatory cytokines; among these IL-1, TNF-α and IL-6 seem to be the most important ones in mediating the cerebral response to infection." (PMID 23905041, 2012). "Secretion of nitric oxide, IL-6, MCP-1, IFN-γ and TNF-α in ex vivo colon biopsies were significantly increased at day 12 following infection with C. jejuni ATCC 43431 or B2 versus naïve animals with supra-physiological intestinal E. coli loads." (PMID 22563475, 2012). "Together these data suggest that extended SchuS4 infection correlates with cessation of production of selected pro-inflammatory cytokines and chemokines, e.g. TNF-α, IL-6, MCP-1 and MIP-1α and continued production of IL-12p40 in target tissues." (PMID 22428026, 2012). "Proinflammatory cytokines such as interleukin-6 (IL-6), and TNF-α secreted by macrophages and monocytes in response to infection play a critical role in immunity." (PMID 22792092, 2012). "The levels of IL-1ß, IL-6, IL-12, and TNF-alpha in mice sera were measured over the first 4 days after infection with Lm, L.inn, and the L.inn::vgc strain." (PMID 22536395, 2012). "Significantly fewer mice succumbed to infection from the TLR2−/− group and symptoms of disease were also reduced in TLR2−/− mice compared to both wild type and TLR4−/− mice, serum levels of IL-6 were significantly reduced in TLR2−/− mice." (PMID 23061052, 2012). "Four days after infection, animals treated with LVF have similar concentrations of IL-6 and MIP-1α in their lungs compared to untreated SchuS4 infected animals." (PMID 22428026, 2012). "Serum levels of IL-12 and IFN-γ peaked early post-infection while TNF-α, IL-6 and IL-1β levels peaked later." (PMID 22545170, 2012). "Pre-mRNAs transcribed from the IL6, IFIT2 and STAT1 genes were present in mock-infected cells, and decreased significantly in concentration following infection with AdEasyE1, whereas only minimal differences in GAPDH mRNA were detected." (PMID 22912576, 2012). "At 4 h post-infection, five chemokines (KC, LIX, MIP-2, MCP-1 and IL-6) were clearly elevated compared to samples from mock-infected animals, in which most chemokines were undetectable and in no case higher than 20 pg/ml." (PMID 22848376, 2012). "Recently, it was shown that L. major infection triggers IL-6 secretion in DC and keratinocytes, and that IL-6 neutralization, together with an exacerbated L. major-induced pathology, increased local TREG cell numbers in the site of infection." (PMID 22545118, 2012). "The accumulation of IL-6 and TNF commenced as early as 1 day after infection with their concentrations increasing with increasing concentrations of C. trachomatis." (PMID 22529524, 2012). "This increased resistance against infection was characterized by augmented levels of bactericidal factors and inflammatory cytokines: ROS, NO, IFNγ TNF IL-6 and IL-12." (PMID 22629382, 2012). "those that are highly upregulated only by infection with virulent S. flexneri (CCL4, CCL20, IFN-γ, IL-1β, IL-4, IL-6, IL-8, IL-12/23p40, IL-21, TNF-α, CAP-18, LeukoP and COX-2); ii." (PMID 22675469, 2012).
infection (continued). "To further investigate the role of PAR-1 in the local inflammatory response, we determined levels of various cytokines (TNF-α, IL-6, IL-10, IL-12, IFN-γ) and chemokines (MCP-1, MIP-2) in lung homogenates at 6, 24 and 48 hours after infection." (PMID 23270594, 2012). "Specifically, secretion of IL-6 and TNF-α from MDM and IL-6 and IL-8 from ATII cells increased at 20 h post-infection." (PMID 23293773, 2012). "Inflammatory cytokines, such as IFNγ, interleukin (IL)-6 and TNFα, and the chemokines, CCL2 and CCL5, were highly upregulated in the respiratory tract after infection with 12500 EID50." (PMID 22496659, 2012). "A549 cells were infected with a multiplicity of infection (moi) of 0.013, 0.04 or 0.13 and supernatant levels of IL-6 and CCL5 were determined at 24 hours post-infection." (PMID 22962966, 2012). "Neutrophil infection induced an IL-6 and TNF-α production that peaked 2 h after infection and declined thereafter." (PMID 22058091, 2012). "More particularly, IL-12, IFN-γ, TNF-α and IL-6 levels were quantified by ELISA in P2Y2+/+ and P2Y2−/− BALFs at days 8, 10 and 12 post-infection." (PMID 23185614, 2012). "The expression of several proinflammatory mediators, including IL-6, IFN-γ, and CXCL1 was significantly reduced in MyD88 KO mice, primarily at the later stages of infection." (PMID 22879997, 2012). "Infection of mice with a mixture of virus and GP resulted in higher levels of the antiviral cytokine IFN-γ and lower levels of proinflammatory cytokine IL-6 compared to those in the mice infected with virus only." (PMID 22442708, 2012). "To confirm the results for the mRNA expression, we studied the protein secretion of cytokine IL6 and chemokine CXCL8 by ELISA at 24 h after the infection." (PMID 22277078, 2012). "The two innate immune gene clusters, IL-6 signaling/complement and IRG cluster, were strongly expressed in ferret lung tissue from 2–14 DPI with SARS-CoV relative to the mock primary infection group." (PMID 23029269, 2012). "At 24 hours after infection, PAR-1 KO mice had substantially lower plasma levels of TNF-α and MCP-1 (P <0.001) and a trend toward lower IL-6 concentrations (P = 0.08) when compared with WT mice." (PMID 23270594, 2012). "Bafilomycin A1 reduced the viral titer of RV14 and inhibited the production of cytokines, including IL-1β, IL-6, IL-8, and TNF-α, and ICAM-1 before and after RV14 infection." (PMID 22966430, 2012). "As the course of disease progresses, IL-6, TNF-α, MCP-1, and MIP-1α are nearly undetectable in the lungs and spleens by day 7 after infection." (PMID 22428026, 2012). "The mutant stimulated less cytokine production in the host lungs, especially at 2 and 3 weeks of infection for both TNF-α and IL6 and at 3 and 6 weeks for IL-1β." (PMID 21687631, 2011). "Disease associated with highly pathogenic influenza viruses and the clinical manifestations that ensue in humans can be mediated by the proinflammatory response (e.g., TNF-α, IL-6, CCL2, CCL3, and CXCL10) initiated by the host in response to infection." (PMID 21829352, 2011). "Experimental infection of pigs with swine influenza virus correlated the clinical signs with the levels of INF-α, interleukin (IL)-6, and tumor necrosis factor-alpha (TNF-α)." (PMID 21592354, 2011). "Infection of both monocytes and macrophages with TCRV also resulted in the release of high levels of IL-6, IL-10 and TNF-α, while levels of IFN-α, IFN-β and IL-12 were not affected." (PMID 21572983, 2011). "In a chicken monocyte/macrophage cell line, induction of proinflammatory cytokines was also found after infection with H9N2 although IL-6 mRNA was down regulated, while in chicken PBMC infected with H11N9 IL-6 mRNA was induced." (PMID 21314972, 2011). "IL-6, IL-8 and MCP-1 are important mediators in the regulation of the acute-phase response to injury and infection by influencing immune cell recruitment, as well as the differentiation and activation of T cells and macrophages." (PMID 21760880, 2011).